IL1B (interleukin 1 beta)
Diseases named in the same sentence as IL1B in open-access papers (continued):
Sharing a sentence is not in itself a finding about the gene and the disease.
psoriasis (continued). "For example, IL1B activates the NLRP3 inflammasome which promotes the secretion of inflammatory factors such as IL-17 and IL-23, which play a key role in the inflammatory response in psoriasis." (PMID 40898481, 2025). "Additionally, the gene expression of IL-6, IL-1b, and IL-17 was investigated in the IMQ-induced psoriasis mice that were treated with anti-IL-17 aptamer." (PMID 39045230, 2024). "The symptoms of psoriasis, such as thickness, erythema, and scaling, and the inflammatory cytokines levels of T-helper (Th)-17-specific cells, such as IL-17 and IL-22, and Th-1-specific cells, such as TNF-α and IL-1β, are reduced by treatment with L-EO in an IMQ-induced psoriasis mouse model." (PMID 38791435, 2024). "However, neither RSL3 nor erastin elicited histological epidermal changes or immune cell infiltration in the skin characteristic of psoriasis, while skin TNF-α and IL-1β expressions were elevated by RSL3 treatment." (PMID 39570671, 2024). "To further investigate whether Gpr15lg can regulate immune response in psoriasis, we detected the level of IL-1α, TNF-α, IL-1β and S100A7 by qRT-PCR and IHC." (PMID 38393364, 2024). "Moreover, AIM2 expression is increased in KCs from skin lesions of patients with psoriasis, and its activation in cultured KCs leads to IL-1β release, suggesting that AIM2 is involved in the pathogenesis of psoriasis." (PMID 39352743, 2024). "Sericin-coated film reduced IL-1β and TNF-α levels in rat psoriasis model." (PMID 38773312, 2024). "In addition, psoriasis related proinflammatory mediators such as TNF‐α, IL‐1β, IL‐17A, and IFN‐γ can induce endoplasmic reticulum stress in a variety of immune cells." (PMID 38174774, 2024). "The gene expression of these key members (Caspase-1, Nlrp3, Gsdmd, Il-1β) was significantly increased in the lesions of psoriasis (P < 0.01) compared with nonlesional skin." (PMID 38125299, 2024). "In IMQ-induced psoriasis skin, both S1pr2-/- and S1pr2fl/fl K14-Cre mice showed higher expressions of proinflammatory cytokines such as TNF-α, IL-17A, and IL-1β together with higher expressions of MyD88/NF-κB pathway compared to the wild-type mice." (PMID 39391307, 2024). "We investigated the recruitment of neutrophils and their expression of IL-1β in the IMQ-induced murine model of psoriasis in the presence or absence of anti-IL-1R1 antibody injection." (PMID 38704587, 2024). "Last but not least, TBTDC NP-PDT attenuated IMQ-induced up-regulation of inflammatory cytokines, including TGF-β1, IL-1β, IL-17, IL-23, TNF-α, IFN-γ, IL-6, and IL-22, which are important proinflammatory cytokines involved in psoriasis pathogenesis in the skin lesions of mice." (PMID 39109246, 2024). "Interestingly, pro-inflammatory cytokines that are upregulated in psoriasis (such as TNF-α, Toll-IL-1R (TIR), and IL-1β) also upregulate miR-9." (PMID 39796035, 2024). "Furthermore, we examined a set of inflammatory cytokines, including IL-17A, IL-23A, IL-1β, TNF-α, IL-6, and IL-22, at the mRNA level in LPS-induced psoriatic keratinocytes, which are closely related to psoriasis in vivo." (PMID 39109246, 2024). "Additionally, we explored the skin lesions of psoriasis patients and found significantly higher expression of CXCL8, IL-1B, S100A9, and S100A12 in the affected skin areas compared to unaffected regions." (PMID 39014096, 2024). "Furthermore, the inflammatory indicators found to be upregulated in psoriasis MCs, such as ATF4, CXCL12, LTA, TACR1, TLR4, and CTSB, interestingly share IL-1β as a common modulator." (PMID 37681909, 2023). "Real-time PCR results further confirmed that the mRNA levels of psoriasis-related factors keratin-17, integrin β1, and CXCL9, as well as the mRNA levels of inflammation-related factors IL-1β, IL-6, TNF-α and iNOS, were strongly inhibited in skin of Mincleflox/flox/Lyz-cre+/+ mice." (PMID 37117184, 2023).
psoriasis (continued). "The transcriptional expressions of Cxcl1, Cxcl2, Il-1β, Il-1α, S100A8, S100A9, Il-6, and Vegf were significantly decreased in skin lesions of K14.Bsgfl/fl mice, indicating the proinflammatory role of the epidermal expression of CD147 in psoriasis." (PMID 37303600, 2023). "The significant upregulation of the MC activator IL-1B and the downregulation of FAM124B and FAM174B, identified as the specific genes in resting MCs, further support the important role of MC activation in the progression of psoriasis." (PMID 36405690, 2022). "Endothelial cells in patients with psoriasis upregulated VCAM-1, IL-1β, and COX-2." (PMID 35457278, 2022). "Interleukin 1 beta (IL-1β) was the most prominent pyroptosis eigengene of psoriasis, followed by absent in melanoma 2 (AIM2) and caspase 5 (CASP5)." (PMID 36110207, 2022). "By using psoriasis mouse models, induced by imiquimod (IMQ) and IL-23, Danay Cibrian found that targeting LAT1-mediated amino acid uptake is a potentially useful immunosuppressive strategy to control skin inflammation mediated by the IL-23/IL-1β/IL-17 axis." (PMID 36276287, 2022). "Our results showed that ELE significantly inhibits the expression of IL1A, IL1B, IL6, and IL8 in M5-stimulated keratinocytes, demonstrating that ELE suppresses the inflammatory responses of psoriasis keratinocytes by attenuating the expression of various interleukins." (PMID 36467042, 2022). "Psoriasis has a high levels of AIM2, the activation of which initiates the assembly of the inflammasome, triggering the maturation and secretion of the cytokine IL-1β (Lugrin and Martinon, 2018, 2)." (PMID 36110207, 2022). "Extensive data reported the role of two variants, namely, rs712829 residing in EGFR gene and rs1143627 in IL1B gene in NCI-60 cancer cell lines and human samples, highlighting the effect of genotype on neoplasms and psoriasis on the usage of diverse drugs molecules." (PMID 36164436, 2022). "Higher caspase-1 and IL-1β levels has been observed in patients with psoriasis that normalized after treatment with TNF-α." (PMID 35265634, 2022). "Besides, the mRNA expressions of macrophage M1-type markers iNOS, IL-1β, TNF-αin imiquimod-induced psoriasis mice were higher than that in Control mice, which were decreased by shikonin and methotrexate treatment." (PMID 35485255, 2022). "In addition, we found that the overall expression of NLRP3, ASC, IL-1β and caspase-1 is higher in the peripheral blood of psoriatic patients compared to normal controls, implying that overactivation of the NLRP3 inflammasome may also contribute to psoriasis-associated inflammatory responses." (PMID 36293012, 2022). "Although the neutralization of IL-1RAcP affects the pathway induced by IL-1α, IL-1β and IL-33, its administration has positive effects in the control of the inflammation in OVA-induced allergic airway inflammation and Imiquimod-induced psoriasis." (PMID 34887860, 2021). "Another group of researchers from China showed that the combination of PlxnB2 and its soluble ligand, CD100, stimulates the production of IL-1β and IL-18 by keratinocytes and activates the NLRP3 inflammasome and the NF-kB pathway during the course of psoriasis." (PMID 34072753, 2021). "IL-37 inhibits the IL-1β, IL-6, and TNF cytokines—which play fundamental roles in psoriatic inflammation—but it can also suppress some chemokines, such as CCL2, which is also important in psoriasis and rheumatic diseases." (PMID 34360845, 2021). "When psoriasis persists or worsens, IFN-α and VEGF released by activated PDCs and keratinocytes provoke myeloid DCs (MDCs) that express proinflammatory cytokines including TNF-α, IL-1β, IL-6, and IL-23." (PMID 34281197, 2021). "Therefore, we examined the possible correlation of key cytokines (IL-1β, TNF-α, IL-4, and IL-6) known to drive crosstalk between KCs and immune sentinels, which results in psoriasis development, with the induction of miR-21-5p or miR-21-3p expression." (PMID 34685526, 2021).
psoriasis (continued). "Drug targets identified by us that are already in use for the different IMIDs include drugs that target IL1B, IL6, TYK2, and JAK2.IL1B was present in the common cell-gene network of AS, CD, psoriasis, RA, and UC, indicating a similar mechanism between these diseases." (PMID 34108969, 2021). "PPPs also attenuated the expressions of CD3 and Ki67 in psoriasis-like mouse skin and suppressed the serum or skin levels of pro-inflammatory cytokines, such as tumor necrosis factor alpha (TNF-α), interleukin 6 (IL-6), IL-1β, IL-8, IL-17, and IL-23." (PMID 35153762, 2021). "In addition, real-time RT-PCR analysis showed that IL-1β, IL-17A, IL-36γ, CXCL1, and CXCL2 expression was increased in IMQ-induced psoriasis-like lesions in Il36rn−/− mice." (PMID 33214582, 2020). "Although metformin reportedly inhibits mature IL-1β secretion via NLRP3 inflammasome in macrophages of T2DM patients, it remains unclear whether it affects skin inflammation in psoriasis." (PMID 32194991, 2020). "Furthermore, Cl-amidine-treated Il36rn−/− mice with psoriasis-like lesions showed decreased TNF-α, CXCL1, IL-1β, IL-36γ, and IL-17A expression compared to those in untreated, IMQ-induced Il36rn−/− mice." (PMID 33214582, 2020). "Dysregulated Th17 cells and IL-17 synthesis in the skin, synovial space and endothelium promote synthesis of pro-inflammatory cytokines namely IL-1β, TNF and IL-6 and neutrophil chemoattractants such as IL-8, CCL20 and CCL2 as observed in psoriasis and psoriatic arthritis." (PMID 33737877, 2020). "These lines of evidence led us to hypothesize that metformin treatment may modulate mature IL-1β secretion via NLRP3 inflammasome in the skin, resulting in the prevention of psoriasis development." (PMID 32194991, 2020). "In addition, TNF-α, CXCL1, IL-1β, IL-17A, and IL-36γ mRNA expression levels in IMQ-induced psoriasis-like lesions were significantly reduced by Cl-amidine administration compared to those in vehicle-treated Il36rn−/− mice." (PMID 33214582, 2020). "We determined the mRNA expression levels of several inflammatory cytokines that are important in psoriasis (TNF-α, IL-23p19, IL-17A, IL-22, IFN-α, IL-1β, IL-6, and IL-10) and a chemokine that promotes the migration of neutrophils (CXCL2) using quantitative real-time PCR." (PMID 32752186, 2020). "Autocrine regulation by TSLP secretion may activate pro‐inflammatory mediators, such as NF‐κB, IL‐1β, and G‐SCF in mutant bulge HF‐SCs and mutant basal keratinocytes, pushing the inflammatory signaling toward psoriasis progression." (PMID 31556482, 2019). "Looking more closely at prominent psoriasis genes, a strong downregulation of IL-17-related genes (IL19, DEFB4, CCL20, LCN2, IL1B) and a less impressive but still significant reduction of IL-17A and IL-23 subunit genes were observed after treatment with both drugs." (PMID 31673756, 2019). "Some features of CD11b deficiency like enhanced activation of NFκB and other TLR-dependent pathways, Th-17 cells expansion, higher activity of DCs and production of some pro-inflammatory cytokines, e.g. IL-1β, IL-6, IL-12, IL-23, and TNF-α, are observed in psoriasis." (PMID 31211819, 2019). "In addition, other pro‐inflammatory cytokines important in psoriasis, such as Il‐6, were only up‐regulated in non‐mutantTom cell populations (Fig EV4J), and we also observed that Il‐1β was significantly up‐regulated in non‐mutantTom b‐KCs (Fig EV4K)." (PMID 31556482, 2019). "The immunohistochemical results showed that the NLRP3 inflammasome signals were observed to be significantly increased in the psoriasis mice; furthermore, the expressions of NLRP3, ASC, caspase-1, and IL-1β were upregulated, which were all inhibited through EPD treatment." (PMID 31181689, 2019). "In addition, TNF- α, IL-1β, IL-6, and INF-γ have been found to increase the production of C3 from the liver and probably from adipose tissue in psoriasis patients." (PMID 29416693, 2018).
psoriasis (continued). "Serum levels of IL-1β, IL-4, IL-10, IL-12, IL-17, IL-21, IL-23, visfatin and omentin were not significantly different between psoriasis patients and controls (all P > 0.05)." (PMID 29416693, 2018). "After the stressful event, the level of IL-1β increased in the control group but not in the psoriasis group." (PMID 29619128, 2018). "Given that IL-1β functions as an initiator and effector for inflammation and skin lesions in psoriasis, we investigated whether CCN1 contributes to IL-1β production in keratinocytes." (PMID 28266627, 2017). "In addition, recent studies indicate that cutaneous and systemic high-level expression of proinflammatory cytokines, such as IL-1β, IL-6, IL-12, IL-18, and interferon-γ (IFN-γ), are typically detected in psoriasis patients." (PMID 26901187, 2016). "In α2/β1 integrin double-transgenic mice, skin irritation led to a chronic condition resembling psoriasis with persistent hyperplasia, cutaneous influx of CD4+ and CD8+ T-lymphocytes and secretion of pro-inflammatory cytokines like TNF-α, IFN-γ, IL-1β and IL-6." (PMID 22590584, 2012). "CD14+ monocytes isolated from both patients with psoriasis and healthy control volunteers were cultured in a cytokine cocktail for 5 days to promote their differentiation into mLCs, then stimulated for 24 h with TNF-α, IL-1β (both 100 ng/mL) or medium alone." (PMID 21933242, 2012). "Additional relevant variables included age, IL-17, TNF, and IFN-γ, while others such as BMI, hs-CRP, TyG index, duration of psoriasis, duration of treatment, HbA1c, smoking, and IL-1β demonstrated negligible or negative importance, indicating limited contribution to model performance." (PMID 41601492, 2026). "The proportions of pro-inflammatory (TNF-α, IL-6, IL-17, IL-23, and IL-1β) and anti-inflammatory (IL-10) cytokines were assessed in the serum and cutaneous tissue of psoriatic animals produced by IMQ to assess the immunomodulatory impact of ERN in psoriasis-like inflammation." (PMID 40667480, 2025). "Although IL-1β and TL1A can similarly activate γδT cells, they might act on different γδT cell populations (e.g. skin-resident versus migratory) and/or in different stages (e.g. inflammation trigger versus progression) during psoriasis development." (PMID 38348035, 2024). "Given that c-Rel deficient DCs are unable to produce inflammatory cytokines including IL-1β and IL-6, we hypothesised that the TLR7/c-Rel signalling axis in DCs regulated the induction of naïve T cells to differentiate into Th17 cells during psoriasis." (PMID 39586195, 2024). "In addition, the HA-ES group loaded with CUR showed relief of inflammatory symptoms according to the clinical psoriasis area and severity index (PASI), lower levels of TNF-α, IL-17A, IL-17F, IL-22, and IL-1β mRNA, and lower CCR6 protein expression compared to ES and PGS groups." (PMID 36678859, 2023). "Functionally, this mechanism resulted in the infiltration of pro‐inflammatory cytokines such as TNF‐α, IL‐1β, IL‐6, IL‐17A, and CXCL‐15, which enhances the inflammatory response in skin lesions and reinforces the cross‐talk between neutrophils and keratinocytes, ultimately aggravating psoriasis." (PMID 35281792, 2022). "Growing evidence also demonstrates the role of the NLRP3 inflammasome and its pro-inflammatory cytokines (e.g., IL-1β and tumor necrosis factor (TNF)-alpha) in patients with psoriasis, suggesting the potential of inhibiting NLRP3 and its cytokines in managing psoriasis and fatigue." (PMID 35663672, 2022). "Moreover,skin-specific NLRP3 suppression can inhibit the proliferation and chemotaxis ofkeratinocytes through the downregulation of IL-1β, IL-23, IL-17A, C-X-Cmotif chemokine ligand 1 (CXCL1), as well as the improvement of Treg/Th17 ratio,thus ameliorating the skin lesions induced by psoriasis." (PMID 39076663, 2022).
psoriasis (continued). "Consequently, we showed that the skin of IMQ-induced mice mimics the psoriatic characteristics with increased infiltration of inflammatory cells and increased levels of psoriasis-related cytokines and chemokines such as CXCL1, IL-25, IL-17A, IL-6, IL-1β, IL-36, CD4, and IFN-γ." (PMID 34641629, 2021). "As epidermal hyperplasia and inflammation are hallmarks of psoriasis, our new findings indicate that alantolactone can not only alleviate these skin lesions by inhibiting inflammation but also relieve epidermal hyperplasia by reducing the expression of TNF-α, IL-6, IL-1β, IL-8, IL-17A, and IL-23." (PMID 34202301, 2021). "Because MAB-hR3 disrupts the recruitment of IL-1RAcP, other inflammatory signals mediated by IL-1α, IL-1β and IL-33 were also disrupted in vitro and in vivo models of local and systemic inflammation models in mice such as peritonitis, OVA-induced airway allergy and Imiquimod-induced psoriasis." (PMID 34887860, 2021). "Particularly, the mast cells makers IL1B is significantly up-regulated in PP, while FAM124B and FAM174B is down-regulated in PP, indicating the mast cells are indeed activated in psoriatic skin and they may play a role in the progression of psoriasis." (PMID 34887864, 2021). "Moreover, IL1B and STAT3 were also reported as hub genes in psoriasis and targets of LXJD formula." (PMID 34168554, 2021). "Moreover, some plants, including Datura Metel L. mustard seed and rosmarinic acid (RA), play a protective role against the development of imiquimod-induced psoriasis by inhibiting NLRP3 inflammasome activation by cytokines, such as IL-1β, IL-6, IL-8, CCL20, and TNF suppression." (PMID 34072753, 2021). "Thus far, several studies have indicated that DCs contribute to the initiation of psoriasis through antigen-presenting molecules (e.g., major histocompatibility complex [MHC], MHCII, CD86, and CD40), cytokines (e.g., interferon [IFN], IL-1β, IL-23, and IL-6), and chemokine receptors." (PMID 34421919, 2021). "Although the inhibition of IL-1β is not fully established as an effective treatment for psoriasis, treatment with IL-1β inhibitors reportedly improved disease in several patients with psoriasis." (PMID 34421919, 2021). "Previous studies demonstrated that the pro-inflammatory cytokines, including TNF-α, IL-6, IL-1β, IL-17A, and IL-22 were up-regulated in psoriatic skin tissues and serum, and the IL-23/IL-17 axis was found to participate in the regulation of IMQ-induced psoriasis-like skin inflammation." (PMID 32515468, 2020). "An increase of general inflammatory (IL-2), innate (IL-1β), IFN-γ, and IL-17–related cytokines (including IL36G) was reported in a heterogeneous group of ichthyosis patients (cohort excluding HI patients); this was similar to the inflammatory response seen in psoriasis." (PMID 32544098, 2020). "IL-1α and IL-1β cytokines stimulate the release of chemotactic cytokines such as IL-8, either directly or in synergy with TNF-α and are involved in the pathologies of several skin diseases including psoriasis, cutaneous lupus erythematosus, atopic dermatitis, and autoimmune blistering diseases." (PMID 31001258, 2019). "The results showed that the mRNA expression of Il1b was higher in MKP-1−/− BMDMs than that in WT BMDMs, indicating that MKP-1 activity in macrophages might be involved in the pathogenesis of psoriasis." (PMID 29619028, 2018). "Thus, we concluded that CCN1 increased IL-1β production via p38 MAPK signaling in keratinocytes, suggesting that CCN1 might be a potential target for ameliorating inflammation in psoriasis." (PMID 28266627, 2017). "In addition, HCRG21 reduced the expression levels of Tnf, Il1β, Il6, Il23a, and Il17a in both psoriatic scab and blood cells and inhibited protein production of IL-23-A and MDC levels compared to the values in the IMQ-induced groups, confirming positive anti-psoriasis dynamics." (PMID 41226679, 2025).